NXT2 (nuclear transport factor 2 like export factor 2)
Description:
Regulator of protein export for NES-containing proteins. Also plays a role in mRNA nuclear export.
Synonyms: P15-2
Tractability: PROTAC: ubiquitination databases record sites on it.
Gene: Protein-coding gene on chromosome X (109,535,781 to 109,544,698, forward strand). Ensembl gene ENSG00000101888.
Subcellular location: Nucleus; Cytoplasm
Subcellular location (Human Protein Atlas): Cytosol; Nucleoplasm
Gene Ontology:
Molecular function: protein binding
Biological process: poly(A)+ mRNA export from nucleus; nucleocytoplasmic transport
Cellular component: cytosol; nuclear RNA export factor complex; nucleoplasm; nuclear pore central transport channel; perinuclear region of cytoplasm; cytoplasm; nucleus
Homologues: Orthologues: chimpanzee NXT2 (100% identical), macaque NXT2 (97% identical), pig NXT2 (92% identical), rabbit NXT2 (92% identical), mouse Nxt2 (87% identical), rat Nxt2 (87% identical), zebrafish nxt2 (70% identical), tropical clawed frog nxt2 (70% identical), guinea pig NXT2 (68% identical), Drosophila melanogaster Nxt1 (39% identical), Caenorhabditis elegans nxt-1 (28% identical). Paralogues in human: NXT1 (73% identical), NUTF2 (24% identical).
Diseases named in the same sentence as NXT2 in open-access papers:
NXT2 is named in the same sentence as 18 diseases in open-access papers, as found by Europe PMC text mining. Sharing a sentence is not in itself a finding about the gene and the disease. The quoted sentences say what the papers report.
Azoospermia (1 paper, 2025). Absence of any measurable level of sperm,whereby spermatozoa cannot be observed even after centrifugation of the semen pellet. "In this study, we demonstrate that testis-enriched NXT2 is indispensable for normal spermatogenesis in humans by identifying two NXT2 variants that abolish protein expression in infertile men with azoospermia." (PMID 40624043, 2025). "M3065 shared the NXT2 LoF variant c.354dup p.(Asp119*) with two further infertile brothers with azoospermia (M3065B1/B3)." (PMID 40624043, 2025). "From a clinical perspective, NXT2 is a strong candidate gene for male infertility due to azoospermia but the identification of additional patients harboring variants in NXT2 is necessary to firmly establish a clinically valid gene-disease relationship." (PMID 40624043, 2025). "Men with loss-of-function (LoF) variants in NXT2 show absence of sperm in the ejaculate (azoospermia) and near absence of germ cells in their testes (non-obstructive azoospermia, NOA)." (PMID 40624043, 2025).
fungal infections (1 paper, 2025). "Nonetheless, these findings highlight the potential of NXT-2 as a single, pan-fungal vaccine candidate and support the rationale for advancing both vaccine- and antibody-based therapeutic strategies to protect vulnerable populations from life-threatening fungal infections." (PMID 41150421, 2025).
infertile (1 paper, 2025). "We, therefore, screened for potentially deleterious genetic variants in NXT2 in exome/genome sequencing data of >2700 well-characterized infertile men from the Male Reproductive Genomics (MERGE) cohort." (PMID 40624043, 2025). "In addition, a further LoF variant in NXT2 was identified in exome data of a second cohort of 667 infertile men from Nijmegen/Newcastle19." (PMID 40624043, 2025). "Focusing on rare (minor allele frequency [MAF] ≤0.001, gnomAD v2.1.1) LoF or high impact missense variants (with CADD score ≥10) and copy number variations in NXT2, we identified two infertile men." (PMID 40624043, 2025).
male infertility (1 paper, 2025). The inability of the male to effect fertilization of an ovum after a specified period of unprotected intercourse. "The study introduces NXT2 as a candidate gene for male infertility and shows that the encoded protein is involved in RNA nucleocytoplasmic transport in human testis by interacting with the RNA export factor NXF1 and proteins of the nuclear pore complex." (PMID 40624043, 2025). "Since NXT2 has a testis-enriched expression profile and may have evolved testis-specific functions, we next addressed the question of whether impaired NXT2 function in the human testis impairs sperm production and causes male infertility." (PMID 40624043, 2025). "In summary, we introduce NXT2 as a strong candidate gene for male infertility and demonstrate that the encoded protein is one key player in adult human testis bulk RNA nucleocytoplasmic transport by interacting with the RNA export factor NXF1 and proteins of the nuclear pore complex." (PMID 40624043, 2025). "Mutations in NXT2 and NXF3 are linked to a disruption of nuclear export, leading to defective germ cell development and human male infertility." (PMID 40624043, 2025). "In addition, we provide evidence that an impaired testis-specific NXT2 interactome leads to male infertility." (PMID 40624043, 2025).
melanoma (1 paper, 2022). A malignant, usually aggressive tumor composed of atypical, neoplastic melanocytes. "With respect to genes associated with other cancers, NXT2 was among 12 genes used to define prognostic risk groups in melanoma." (PMID 35574500, 2022).
osteosarcoma (1 paper, 2021). A usually aggressive malignant bone-forming mesenchymal neoplasm, predominantly affecting adolescents and young adults. "Our results showed that compared with osteoblasts, CPEB3, EIF4E3, RBM34, RPS27L, RPS29 and TDRD6 were down-regulated in U2OS and 143B, while NXT2, TERT, TLR8 and ZC3HAV1 were up-regulated in osteosarcoma cells." (PMID 34926575, 2021).
vulvovaginal candidiasis (1 paper, 2025). Infection of the vulva and vagina with a fungus of the genus CANDIDA. "Additionally, we recently reported that NXT-2 immunization affords protection in a murine model of vulvovaginal candidiasis due to Candida albicans and that anti-NXT-2 antibodies promote antifungal activity." (PMID 41150421, 2025).
cancer (5 papers, 2015 to 2025). A tumor composed of atypical neoplastic, often pleomorphic cells that invade other tissues. "This analysis also highlighted a few interesting context dependent SL gene pairs such as NXT1/NXT2, recently described as a synthetic lethal interaction in paediatric cancer models." (PMID 40968372, 2025). "We also noted that “cancer-specific” escapees, such as HDAC8 or NXT2, exhibit additional and/or enlarged H3K4me3 sites in tumor cells when compared to HMEC." (PMID 25653311, 2015). "But so far, TDRD6, NXT2, RBM34 have not been described in cancer." (PMID 34926575, 2021).
infection (2 papers, 2021 to 2025). The state of being infected such as from the introduction of a foreign agent such as serum, vaccine, antigenic substance or organism. "The immunogenicity of the CAu.KEX1 during infections and the cross-reactivity of this protein with antibodies generated to the consensus protein NXT-2 provided the rationale for investigating NXT-2 as a vaccine candidate in an invasive C. auris infection model." (PMID 41150421, 2025). "Among the ribosomal proteins, Treacle ribosome biogenesis factor 1(TCOF1), nuclear transport factor 2 like export factor 2(NXT2), ribosomal protein L37(RPL37), ribosomal protein L29 (RPL29) and mitochondrial ribosomal protein S18A(MRPS18A) are all up-regulated in the early stages of infection." (PMID 34092256, 2021).
cardiac diseases (1 paper, 2005). "It should be a reasonable step to determine genetic linkage relationship between a NXT2 locus and defined cardiac diseases." (PMID 15790397, 2005). "Since NXT2 is highly conserved between fish and man it is conceivable that it may also play a role in mammalian heart development and might be involved in cardiac diseases." (PMID 15790397, 2005).
NXT2 also shares sentences with these, for which no sentence is quoted: tumor (2 papers); breast tumors (1); Hypercalciuria (1); Hypomagnesemia (1); lung carcinoma (1); malaria (1); nephrocalcinosis (1); Obstructive azoospermia (1).